ANXA2 (annexin A2)
Diseases named in the same sentence as ANXA2 in open-access papers (continued):
Sharing a sentence is not in itself a finding about the gene and the disease.
tumor (continued). "ANXA2 serve as a potent target of therapeutic intervention and multiple therapeutic strategies targeting ANXA2 have been testified and showed favorable anti-tumor efficacy both in vitro and vivo." (PMID 33995636, 2021). "Cytoskeletal-associated proteins play an active role in coordinating the adhesion and migration machinery in cancer progression, and targeting annexin A2 could effectively inhibit tumor cell adhesion, migration and in vivo grafting." (PMID 34484309, 2021). "Numerous in vitro and in vivo studies, as well as studies on humans, prove that targeting overexpressed molecules, such as mucin 16 (MUC16), annexin 2 (ANXA2), receptor tyrosine-protein kinase erbB-2 (HER2/neu) causes high tumour cells toxicity and decreased tumour burden." (PMID 33800608, 2021). "Moreover, the expression of ANXA2 is positively correlated with histological type, tumor size, depth of invasion, and pathological tumor-node-metastasis stage." (PMID 33995636, 2021). "High ANXA2 expression was significantly correlated with high tumor grade." (PMID 34048174, 2021). "As such, the depletion of ANXA2+ cells from the tumour could potentially inhibit tumour growth via the removal of an angiogenic pathway." (PMID 31936170, 2020). "In tumor cells ANXA2 regulates adhesion, invasion, proliferation, and migration." (PMID 32197509, 2020). "Regarding ANXA2 immunohistochemistry results, it is important to highlight that when there was positive immunoreactivity it was mostly seen in the cytosolic compartment of human tumor samples." (PMID 32197509, 2020). "Thus, ANXA2 plays a key role in establishing PCa bone metastasis, facilitating the tumor cells homing in the bone marrow." (PMID 32197509, 2020). "This is consistent with the membrane proximal position of ANXA2 on the surface of tumour cells." (PMID 31936170, 2020). "Interestingly, instead of MYC, calcium-dependent phospholipid-binding protein ANXA2 was downregulated in PD tumor of old men forming a key central node." (PMID 33575208, 2020). "ANXA2 is upregulated in several tumors and plays critical roles in tumor development." (PMID 32248843, 2020). "Thus, the reduced Ca2+ concentration in the CM, as a consequence of the presence of tumor cells in the co-culture, is consistent with the internalization of ANXA2 from the plasma membrane to the cytoplasm in the osteoclastic precursors." (PMID 32197509, 2020). "While ANXA2 overexpression significantly shortened the survival of tumor-bearing mice compared with control mice (median survival = 94.5 days vs 101 days, P = 0.0094), concomitant silencing of OSMR significantly prolonged mouse survival (median survival = 131 or 137.5 days, both P = 0.0029)." (PMID 32248843, 2020). "The involvement of annexin A2 in tumor progression may be related to the overproduction of plasmin on the surface of aggressive cancer cells, on the surface of endothelial cells, or both." (PMID 32575495, 2020). "However, while the tumours of mice treated with control CAR(αCD19)L-BBz T cells were ANXA2+, the expression of ANXA2 was greatly diminished in the tumours of mice treated with CAR(2448)L-BBz T cells (p < 0.05)." (PMID 31936170, 2020). "The anti-tumor efficacy of Lm-ANXA2 still appears to be modest." (PMID 31113479, 2019). "In the meantime, we determined whether combination treatment with Lm-ANXA2 and anti-PD-1 blockade increases ANXA2-specific T cell response in the tumor microenvironment." (PMID 31113479, 2019). "Furthermore, ANXA2 expression was significantly correlated with differentiated degree, intrahepatic metastasis, portal vein thrombus, and tumor node metastasis (TNM) staging." (PMID 30881525, 2019). "We hypothesized that an ANXA2-targeting vaccine approach not only provokes an immune response but also mounts anti-tumor effects." (PMID 31113479, 2019). "Moreover, in the xenograft model, miR-204/211, miR-148a/152 and sh-ANXA2 suppressed the tumor growth enhanced by LncCCAT1 overexpression." (PMID 31695775, 2019).
tumor (continued). "As ANXA2 plays a crucial tumor-promoting role in GBM and since ANXA2 levels are modulated by miR155HG and miR-185-5p, we hypothesized that miR155HG and miR-185-5p could interfere with the proliferation and apoptosis of GBM cells." (PMID 30898167, 2019). "HE4 and ANXA2 are co-localized in the cytoplasm and membrane of various tumor cells." (PMID 31210752, 2019). "The optimal activation of ANXA2 epitope specific T cells in the tumor microenvironment may be reliant on anti-PD-1 antibodies." (PMID 31113479, 2019). "Although KPC mice treated with Lm-ANXA2 followed by anti-PD-1 antibody demonstrated a statistically significant improvement in the anti-tumor effect comparing to untreated KPC mice, all of the mice, treated or untreated, eventually had disease progression and died." (PMID 31113479, 2019). "ANXA2 is closely related to the occurrence and development of several malignant tumors and plays an important role in angiogenesis, proliferation, apoptosis, adhesion, invasion and migration of tumor cells." (PMID 31210752, 2019). "In the reactive astrocytes from the tumor we identified an increased expression of immune associated genes such as CHI3L1, HLA-DRA, CD274, HLA-DRB3, CD37, as well as genes that contributed to proliferation (MKI67, ANXA2) and complement components (C1S, C1R)." (PMID 31186414, 2019). "This suggests that Lm-ANXA2 alone may have a limited capability of inducing antigen-specific, IFNγ expressing T cell infiltration into the tumor microenvironment." (PMID 31113479, 2019). "ANXA2 is overexpressed in most tumor tissues and acts as a pivotal part in tumor development." (PMID 31186633, 2019). "Similarly, the high expression of stromal ANXA2 was significantly correlated with short disease-free survival and overall survival, while the high expression of ADAM9 was associated with poor tumor differentiation and short overall survival in PDAC patients." (PMID 30700038, 2019). "We used human CRC samples to analyse the correlation between ANXA2 levels and tumour staging." (PMID 30050103, 2018). "In addition, we observe increased ANXA2 levels in stage IV tumours and metastasis, when compared to stage I-III." (PMID 30050103, 2018). "Knockdown of ANXA2 in tumor cells might decrease the number of and limit the function of enlargeosomes." (PMID 29598816, 2018). "miR-889, Cyclin D1, Annexin A2) and less tumor-suppressive RNA (ex." (PMID 30546829, 2018). "Annexin A2 is a widely distributed, highly conserved, peripheral membrane protein expressed abundantly on endothelial cells, macrophages, myeloid cells and some tumor cells." (PMID 30341243, 2018). "Taken together, this study for the first time demonstrated that G-Rg5 and G-Rk1 inhibit tumor cell growth by targeting Annexin A2 and NF-κB pathway, and G-Rg5 and G-Rk1 might be promising natural compounds for targeted cancer therapy." (PMID 29508276, 2018). "As described, Annexin A2 binds to NF-κB p50 subunit, and promotes NF-κB activation, which might promote the pro-survival effect and chemoresistance in tumor tissues." (PMID 29508276, 2018). "Although extracellular ANXA2 was reported in diverse cell types including endothelial and tumor cells, surface epitopes on ANXA2 may be challenging to recapitulate (for antibody generation purposes)." (PMID 29568351, 2018). "It is noteworthy that, the effect of chemosensitivity changing with ANXA2 knockdown seems weaker in vivo: not only minor decrease of tumor volume in knockdown group compared with control group, but also no significance difference with pro-apoptotic factors as AIF and cleaved-PARP." (PMID 28814318, 2017). "Previously studies indicated that several relevant downstream signals, such as AKT and MAPK, might involve in tumor-promoting effects of Annexin A2." (PMID 28886730, 2017).
tumor (continued). "This yielded 88 genes associated with tumor grade, in which seven DEGs (C8orf33, TSNAXIP1, TM4SF1, CTH, ANXA2, KIAA1522 and LRRC1) can distinguish HCC of G3 from G1, two DEGs (CYB5A and RRAGD) can distinguish HCC of G3 from G2, and two DEGs (CFHR4 and F13B) can distinguish HCC of G3 from G4." (PMID 29123978, 2017). "In conclusion, here we show that a prototype peptide such as cell-internalizing LGRFYAASG-pen mechanistically interferes with intracellular annexin A2, representing a multifaceted inhibitor of cytoskeletal arrangements pivotal for key steps in cancer progression in preclinical tumor models." (PMID 28652618, 2017). "Annexin A2 plays multiple roles in tumor cell proliferation and metastasis." (PMID 28963461, 2017). "ANXA2 on the tumor cell surface mediates tumor invasion and promotes malignant progression." (PMID 28720835, 2017). "High expression of ANXA2 correlated with tumor metastasis and poor prognosis." (PMID 28814318, 2017). "Several studies show concordance between tumoral and stromal expression of tumor markers suggesting that AnxA2 expression in both tumor cells and stromal cells might play a significant role in PDA metastasis." (PMID 29290958, 2017). "Recent data indicated that P37 promoted tumor progression through its interaction with ANXA2 in host cells, while P37 antibodies, a polypeptide A2PP (a 30 amino acids polypeptide within the N-terminal of ANXA2), and anti-mycoplasma reagent like MYCO I, were able to block this interaction." (PMID 28976984, 2017). "Aberrant Annexin A2 expression has oncogenic effects in several tumor types." (PMID 28886730, 2017). "To confirm the ANXA2 and its pseudogenes expression with clinical specimens, we detected the expression levels of ANXA2 and its pseudogenes in 99 diffuse glioma specimens and 12 non-tumor brain tissues by qRT-PCR." (PMID 29291003, 2017). "We found that knockdown of Annexin A2 moderately inhibited tumor growth." (PMID 28886730, 2017). "The future may bring novel approaches to increase the immunogenicity of ANXA2 within tumor cells as a strategy to increase anti-tumor immunity in vivo." (PMID 26885373, 2016). "Our results revealed that Annexin A2-high subgroup had larger tumor size (p = 0.016)." (PMID 27121050, 2016). "ANXA2-antigen fusion peptides could be developed for patients as “off-the-shelf” agents containing common tumor antigens." (PMID 26885373, 2016). "In addition to its expression in cancer cells, annexin A2 is expressed by other cell types found in tumour microenvironment, thus contributing to cancer progression." (PMID 27196940, 2016). "Strikingly, when integrating the transcriptome under HO-1 modulation with the HO-1 interactome, a framework of four main molecular pathways arose as the foundation for the regulation of the tumor cell protrusive forces: ANXA2/HMGA1/POU3F1; NFRSF13/GSN; TMOD3/RAI14/VWF; PLAT/PLAU." (PMID 28032857, 2016). "The result confirmed that the expression levels of ONECUT2, IGF2BP1, and ANXA2 were significantly elevated in non-tumor tissues compared to normal tissues (P = 0.0116, P = 0.0380 and P = 0.0145, respectively), and further elevated in HCC tissues (P = 0.0270, P = 0.0003 and P < 0.0001, respectively)." (PMID 26547929, 2015). "ANXA2 plays an important role in biological activity and tumor progression." (PMID 26362938, 2015). "When shNPC-2 cells were used as a xenograft in mice, the tumor growth was dramatically inhibited compared to the control mice, suggesting a potent antitumor effect of ANXA2 knockdown, which may involve a restoration from DC-mediated immune suppression." (PMID 25402728, 2015). "Further studies may be needed to distinguish the effects of exoplasmic from cytoplasmic ANXA2 on tumor growth." (PMID 25402728, 2015). "Vasculogenic mimicry (VM) is important way for tumor development and angiogenesis, and silencing of ANXA2 suppressed the vascular formation ability which indicates that ANXA2 may suppress angiogenesis." (PMID 26196246, 2015).
tumor (continued). "Interestingly, we observed the abundant expression in the tumours of several proteins known to be involved in angiogenesis, including ANXA2, CA2, ATP5B and HSPB1." (PMID 25980435, 2015). "The results indicated that ANXA2 promoted tumor cell proliferation both in vivo and in vivo and suggested that ANXA2 could be a molecular target for treatments aimed at decreasing oncogenesis." (PMID 26196246, 2015). "Molecular studies have suggested that CTX binds and internalizes into a wide range of tumor types via the annexin A2 complex, a ubiquitously expressed intracellular protein in normal cells that is found expressed in complexes on the exterior surface of extracellular membranes of transformed cells." (PMID 24982846, 2014). "Annexin A2 expression was 3+ in the untreated tumor and 2+ in the treated tumor." (PMID 25298748, 2014). "Moreover, the expression of ANXA2 is positively correlated with histological type, tumor size, depth of invasion, and pathological tumor-node-metastasis (pTNM) stage." (PMID 24591759, 2014). "S100A10 acts as a key molecule for the promotion of angiogenesis and tumor metastasis, and annexin A2 is believed to act as a scaffolding protein to secure S100A10 to the cell surface, considering the well-established roles of S100A10 in cellular plasmin regulation." (PMID 24851084, 2014). "The expression of annexin A2 in the tumor tissue of a patient with UTUC was higher than in the normal tissue of the same patient by western blotting analysis and immunohistochemistry and the over-expression was also found in the tumor areas of eleven tumor/adjacent normal tissue pairs (84.6%)." (PMID 24884814, 2014). "ANXA2 is expressed in some tumor cells, endothelial cells, macrophages, and mononuclear cells." (PMID 24591759, 2014). "The antibody blockade of surface ANXA2 can inhibit tumor cell growth and metastasis." (PMID 24591759, 2014). "ANXA2 is a novel signalling mediator of HBV-related chronic inflammation-induced tumour metastasis." (PMID 24348815, 2014). "The mRNA and protein expression of ANXA2 is lower in only 22 ESCC tumor cells in the patient tissues than that in its paired normal counterpart, and this downregulation is significantly correlated with lymphoid node metastasis (P < 0.05) and pathological differentiation (P < 0.05)." (PMID 24591759, 2014). "The ACE4 aptamer might be useful for such purposes since it could be internalized inside cells upon binding to Annexin A2 and has already demonstrated promising in vivo tumor targeting by in vivo imaging." (PMID 24489826, 2014). "In addition to metastasis and invasion, previous studies have shown that ANXA2 is involved in tumor cell proliferation." (PMID 24591759, 2014). "Furthermore, strong cell surface expression of ANXA2 is observed in tumor cells and stromal cells surrounding the blood vessels." (PMID 24591759, 2014). "Assessment of cytochrome C and annexin A2 expression in the untreated tumor was not feasible due to loss of tissue." (PMID 25298748, 2014). "Furthermore, proteins isolated from tumor cells depleted of annexin A2 also show more oxidation compared to control cells." (PMID 23519104, 2013). "There was no statistical association between serum ANXA2 and age, gender, tumor differentiation or tumor size (data not shown)." (PMID 23946789, 2013). "Consequently, we have observed that annexin A2 depleted tumor cells present with significantly increased levels of ROS, and also showed increased oxidation of redox sensitive cellular proteins upon H2O2-mediated oxidative stress." (PMID 23519104, 2013). "Annexin A2 expression in cancer is relatively paradoxical as it may act as a tumor suppressor or as an oncogene depending on the type of cancer." (PMID 23519104, 2013).
tumor (continued). "Fifteen proteins were upregulated, including annexin A2, annexin A1, superoxide dismutase [Mn], peroxiredoxin-1, translationally-controlled tumour protein and α B-crystallin in the model group compared to the control group and downregulated upon treatment with RuXian-I." (PMID 23434659, 2013). "In addition, the tumor-associated proteases play an important role in tumor migration through degradation of extracellular matrix (ECM), and we found that Annexin A2, a member of family of tumor-associated proteases, is highly expressed in GBM1." (PMID 23875172, 2013). "Furthermore, annexin A2 neutralizing antibodies were used to examine the role of annexin A2 in tumor invasion and metastasis in vivo using a chick chorioallantoic membrane assay and an intraperitoneal xenograft mouse model." (PMID 23945256, 2013). "Recently, we analysed the role played by annexin A2 in tumour growth." (PMID 23434659, 2013). "To further investigate the mechanisms of ANXA2 in tumor progression, we introduced CD147, which has been hypothesized to interact with ANXA2 but which has not yet been shown to do so." (PMID 23950866, 2013). "Furthermore, it is been linked to carcinogenesis and the progression of invasive cancer, suggesting an AnxA2-specific function that is necessary for tumour development." (PMID 22505935, 2012). "Recent studies suggest that interactions between Anxa2 and its binding proteins may play important roles in the tumor microenvironment and they act together to promote cancer metastasis." (PMID 23691462, 2012). "Indeed, AnxA2 KO mice are incapable of supporting the growth of solid tumours in an implantation assay, consistent with a role for AnxA2 in tumour progression." (PMID 22505935, 2012). "Our in vivo tumor studies showed that tumor growth in animals injected with either ANXA2 depleted HT1080 or ANXA2 depleted A549 cancer cells was severely impaired compared to tumor growth in animals injected with control HT1080 and A549 cancer cells, respectively." (PMID 22185818, 2011). "Furthermore, recently, annexin A2 was identified as a binding partner for TM601 in multiple human tumor cell lines and normal human endothelial cells HUVEC." (PMID 21838899, 2011). "However, in mice receiving NAC injections, the labeling of tumor extracts by BIAM suggested similar levels of protein oxidation between tumors grown from ANXA2 depleted or control HT1080 cells." (PMID 22185818, 2011). "The induction ofantibodies against ANXA2 that is observed in vaccinated patients with prolongedDFS suggests that anti-ANXA2 antibodies may have a direct anti-tumor effect." (PMID 21572519, 2011). "In order to investigate if the growth impairment observed for the ANXA2 depleted tumors was due to ROS overload, we repeated the tumor growth experiments using ANXA2 depleted HT1080 and control cells and administered the antioxidant agent, NAC intraperitoneally every two days." (PMID 22185818, 2011). "Recent studies have verified that Galectin-1 and other proteins identified in -BD11 ECM, e.g. aminopeptidase-N annexin-A2 or nucleolin, can serve as tumour targets, with evidence that combined targeting of perivascular and endothelial cells can enhance anti-tumour treatment." (PMID 21779348, 2011). "Especially, ANXA2 has an important role in angiogenesis and tumor progression, and, thus, might be a potential therapeutic target." (PMID 21918681, 2011). "In addition, S100A10 and Annexin A2 form isodimers, prompting the invasion and metastasis of the tumor by activating plasminogen." (PMID 19638242, 2009). "Furthermore, the plasminogen activation system operates through specific cell surface receptors like annexin A2/S100A10 complexes that can be delivered to distant organs via tumor-derived exosomes (or activated locally in the resident fibroblasts and immune cells)." (PMID 41463352, 2025). "Furthermore, the roles of ANXA2 in tumour inflammation and immunity remain poorly understood." (PMID 40234383, 2025).